MICA (MHC class I polypeptide-related sequence A)
Diseases named in the same sentence as MICA in open-access papers (continued):
Sharing a sentence is not in itself a finding about the gene and the disease.
lung carcinoma (20 papers, 2010 to 2025). "Antibodies targeting VEGFR2 fused with MICA stimulate antiangiogenic effects, showing clinical benefits in cancer therapy, particularly in gastric and lung cancers." (PMID 38397233, 2024). "Due to the lack of studies on SCLC samples in the database, we analyzed the prognostic significance of MYC and MICA/B expression levels in lung cancer using Kaplan-Meier plotter to investigate the clinical significance of MYC and NKG2DL." (PMID 35158730, 2022). "Treating NCI-H23 and A549 lung cancer cells with FK228 led to an increase in the transcription of the five NKG2D ligands: MICA, MICB, ULBP1, ULBP2, and ULBP3." (PMID 34203519, 2021). "In contrast, expression of the oncomiR-183, up-regulated by TGF-β in lung cancer, was shown to down-regulate MICA and MICB glycoprotein expression in lung tumor cell lines through a binding site in the 3'-UTR of MICA/B transcripts." (PMID 31803194, 2019). "Of note, similar data have been reported in the literature where erlotinib induced downregulation of MICA in lung cancer cells and still enhanced sensitivity to killer cells." (PMID 31546690, 2019). "In our studies, IHC data indicated a large proportion of cytoplasmic MICA/B expression instead of cell surface staining in lung cancers and gynecologic malignant tumors." (PMID 29221214, 2017). "The lung cancer cell line A549 highly expressed MICA, MICB, ULBP1, and ULBP2/5/6." (PMID 35965586, 2022). "Next, we adopted flow cytometry to assess cell surface expression of NKG2DLs, MICA/B and ULBP1 on the lung cancer cell lines including A549, H1975, and PC9." (PMID 38263004, 2024). "Epidermal growth factor receptor (EGF-R), CD20 and MICA and MICB were expressed on the surface of A549 lung cancer cells and Raji B-cell lymphoma cells." (PMID 35967081, 2021). "The transcription of NKG2D ligands, namely, MHC class I polypeptide-related chain proteins A (MICA), MICB, UL16 binding protein 1 (ULBP1), ULBP2, and ULBP3, was analyzed after treating lung cancer cells with five types of HDAC inhibitor for 18 h." (PMID 34203519, 2021). "In our short-term co-culture system, A549 and H1975 lung cancer cells down-regulated surface expression of NKG2D ligands ULBP1, ULBP2 and MICA following co-culture with NK cells." (PMID 23937717, 2013). "To investigate whether gefitinib could up-regulate surface ligands for NK cell activating receptors, we co-cultured two human lung cancer cell lines with NK cells and evaluated the expression of ULBP1, ULBP2 and MICA by flowcytometry." (PMID 23937717, 2013). "We found that the patients with high MYC mRNA expression had worse OS (HR 1.38 [1.02–1.86], p = 0.0035), and the patients with high MICA mRNA expression had better OS (HR 0.7 [0.52–0.95], p = 0.019) which also suggested the negative correlation between MYC and MICA in lung cancer." (PMID 35158730, 2022).
leukemia (18 papers, 2012 to 2026). A malignant (clonal) hematologic disorder, involving hematopoietic stem cells and characterized by the presence of primitive or atypical myeloid or lymphoid cells in the bone marrow and the blood. "It recognized multiple MICA alleles expressed in human gastric and leukemia cell lines, confirming broad allelic coverage." (PMID 41756291, 2026). "According to their observation, homozygotes with microsatellite alleles A5 and allele MICA*010 have increased risk for developing leukemia (specifically for AML, the ratio of frequency was 35.9% in patients with AML vs. 17.6% in control samples)." (PMID 33868289, 2021). "At diagnosis, MICA showed the highest expression in all leukemia entities, although this difference was statistically significant only in B-ALL samples." (PMID 37928520, 2023). "Previous studies reported that exosomal MICA inhibited NK cell cytotoxicity in several cancer types such as melanoma and leukemia." (PMID 31181729, 2019). "For instance, the NKG2D ligand, MICA/B, was frequently expressed in solid tumor and leukemia and soluble MICA/B downregulates NKG2D expression, resulting in decreased killing potency." (PMID 31547251, 2019). "Exosomes from solid tumors or leukemia/lymphoma cells can present MICA, MICB, and ULBP molecules leading to an inhibition of the NKG2D-mediated NK cell activation." (PMID 27014273, 2016). "Soluble NKG2DLs (sNKG2DLs), such as MICA that is shed from the surface of prostate cancer, ovarian cancer, and leukemia cells, bind to NKG2D on NK cells, this blocks the recognition of NKG2DLs expressed in cancer, resulting in tumor immune escape from NK cell surveillance." (PMID 31181729, 2019). "Studies have shown reduction of MICA/B surface expression that may impair NKG2D-mediated immune surveillance of leukemia." (PMID 29963052, 2018). "In addition, a higher relapse rate was observed in patients with MICA-129 met as compared to those with MICA-129 val/val genotype because of reduced graft versus leukemia effect of NK and CD8+ cells consequent to downregulation of NKG2D by MICA-129 met variants." (PMID 28293239, 2017). "Thus, HDAC1 may inhibit the transcription of MICA/B on leukemia cells, whereas HDAC3 may repress the transcription of ULBP1–3 in epithelial tumors." (PMID 24711808, 2014). "We examined the expression of NKG2D ligands in leukemia cell lines treated with low concentration AACOCF3 (5μM) and found that expression levels of the MICA, MICB, and ULBP family were all significantly elevated." (PMID 36338749, 2022). "With the exception of MICA that was barely detectable in CEM and MOLT-4 cells, all tested NKG2DLs were expressed in the three cell lines, consistent with the presence of at least one of these molecules on leukemia cells of most patients." (PMID 30867508, 2019). "Thus, BCR/ABL induces the MICA surface expression on CML leukemia cells, whereas it was absent on healthy hematopoietic cells." (PMID 24711808, 2014). "The lack of NKG2D ligands (MICA, MICB, or others) is a trait of resistant leukemia stem cells." (PMID 32516941, 2020).
colorectal cancer (15 papers, 2014 to 2025). A primary or metastatic malignant neoplasm that affects the colon or rectum. "In our study, we reported SD in 4 patients with colorectal cancer, and we observed that SD could be linked to the low baseline level of soluble MICA and reduction of circulating Tregs after treatment with NEO-201." (PMID 36991390, 2023). "However, the genetic association, potential function, and predictive ability of MICA alleles with colorectal cancer (CRC) prognosis remain undefined." (PMID 32528529, 2020). "However, this variant was less frequent in patients with colorectal cancer, indicating that MICA alleles play a different role depending on the type of cancer, possibly due to cellular and molecular mechanisms that are particularly associated with different types of tumors." (PMID 33868281, 2021). "MICA mRNA expression was significantly higher in colorectal cancer tissues compared to normal tissues, and ROC analysis indicated an AUC of 0.7456, with a CI of 0.556-0.9341, and a p-value of 0.0333." (PMID 40726981, 2025). "Specifically, in colorectal cancer cell lines, MICA mRNA expression was elevated in the tRF-3021a interference group, whereas it was suppressed in the tRF-3021a overexpression group." (PMID 40726981, 2025). "Malignant tumors derived from the digestive system, such as gastric cancer, colorectal cancer, and liver cancer, all have high levels of MICA or MICB expression, as well as high levels of MMPs or ADAMs." (PMID 40563539, 2025). "Early reports indicated that elevated MICA or MICA/B and RAET1G (ULBP5) were linked to improved prognosis in colorectal cancer." (PMID 37626965, 2023). "A study using human colorectal carcinoma cell lines demonstrated that MICA and MICB mRNA and surface protein expression were low when cells were at high confluency and quiescent." (PMID 33352921, 2020). "Moreover, both MICA mRNA and protein expression were significantly elevated in colorectal cancer cell lines." (PMID 40726981, 2025). "Notably, ELISA analysis of the colorectal cancer cell supernatants revealed an inverse relationship between the expression of soluble MICA (sMICA) and mMICA." (PMID 40726981, 2025). "Furthermore, we analyzed MICA expression using the TCGA database and experimental validation, as the role of MICA in colorectal cancer remains underexplored." (PMID 40726981, 2025). "Notably, the expression level of MICA was significantly higher in colorectal cancer tissues compared to normal tissues, as observed in the TCGA database." (PMID 40726981, 2025). "MICA and MICB are also expressed on the surface of colorectal cancer cells derived from intestinal epithelium cells." (PMID 40563539, 2025). "This, in turn, facilitates colorectal cancer progression through an NKG2D receptor-mediated immune escape mechanism, resulting in the inhibition of NK cell activation by promoting MICA shedding via ADAM10." (PMID 40726981, 2025). "MiR-17-5p has been documented to suppress the expression of MICA and MICB, two other important NKG2DLs, in hepatocellular and colorectal cancers." (PMID 39963142, 2025). "In a similar study performed on the human colorectal carcinoma cell line CaCo-2, oxidative stress induced by H2O2 also increased MICA and MICB mRNA expression, although surface protein levels were not measured." (PMID 33352921, 2020). "tRF-3021a is highly expressed in colorectal cancer, and by upregulating ADAM10 protein expression, cleave membrane MICA forms more soluble MICA, blocking the cytotoxic effect of NKG2D activated receptors in NK cells, and ultimately leading to immune escape in colorectal cancer." (PMID 40726981, 2025).
psoriasis (15 papers, 2009 to 2024). An autoimmune condition characterized by red, well-delineated plaques with silvery scales that are usually on the extensor surfaces and scalp. "Specifically, MICA*010 was identified as a common risk factor for psoriasis and RA in Taiwanese subjects." (PMID 38474281, 2024). "The current study sought to further evaluate the impact of MICA variants on the development of psoriasis (PSO), RA, and SLE." (PMID 38474281, 2024). "Functional MICA alleles are distinctively associated with the pathogenesis of psoriasis and RA in Taiwanese subjects." (PMID 38474281, 2024). "The MICA*002 allele with high avidity protects against psoriasis and RA, whereas the deficient MICA*010 allele increases the risk for psoriasis and RA development." (PMID 38474281, 2024). "Of note, we were unable to detect sMICA in RA and psoriasis patients carrying the homozygous MICA*010 allele, confirming that MICA*010 is a deficient allele for mature MICA expression." (PMID 38474281, 2024). "SNP rs13437088, situated at the 16 kb telomeric region of MICA and 30 kb centromeric region of HLA-B, exhibited a robust association with Han Chinese psoriasis after adjusting the effect of the imputed HLA-Cw*0602." (PMID 38474281, 2024). "Although MICA is strongly in LD with HLA-B, it has been associated with psoriasis and evidenced for an association independently of HLA-B/C with psoriatic arthritis in Jewish population." (PMID 22125590, 2011). "The second locus we observed after adjustment for HLA-C and C6orf10 is between HLA-B and MICA, located 117 kb centromeric to HLA-C, suggesting the potential association of HLA-B or MICA with psoriasis risk." (PMID 19680446, 2009). "The current study evaluated whether MICA polymorphisms distinctively influence the pathogenesis of psoriasis (PSO), rheumatoid arthritis (RA), and systemic lupus erythematosus (SLE) in Taiwanese subjects." (PMID 38474281, 2024). "MICA gene variations are associated with risk of immune‐mediated disease, a meta‐analysis shows that the MICA‐TM A9 allele is associated with psoriasis susceptibility in Asian populations and that the MICA‐TM A9 allele is associated with a psoriatic arthritis risk in Europeans." (PMID 36196481, 2022). "We examined the impact of MICA alleles, which are formed by all coding SNPs, on the susceptibility to SLE, RA, and psoriasis in Taiwanese subjects." (PMID 38474281, 2024). "Our data suggest that the deficiency of MICA, a critical immune-stimulatory ligand for NKG2D, is an underlying mechanism for the susceptibility to psoriasis and RA." (PMID 38474281, 2024). "Similar studies have also identified SNPs in the MHC class I region or close to MICA and MICB that associate with multiple sclerosis and psoriasis." (PMID 39283896, 2024). "In contrast, MICA*002, MICA*009, and MICA *012 played a protective role against the development of psoriasis." (PMID 38474281, 2024). "For GRU group, rs13437088 [P(T) = 8.09E-17)], located 30 kb centromeric of HLA-B and 16 kb telomeric of MICA (MIM: 600169), had been previously reported to be associated with psoriasis." (PMID 31024629, 2019). "Meanwhile, there is a pseudogene XXbac-BPG299F13.15 which is located in the same LD region as HLA-C and is interacting with 4 other literature reported psoriasis-associated genes (PSORS1C1, MICA, HCP5, HLA-C)." (PMID 30315195, 2018). "The MICA*010-HLA-B*4601-Cw*01 haplotype displayed a greater incidence of Type I and II psoriasis." (PMID 38474281, 2024). "Another study, examining whole blood methylation differences in psoriasis, identified three regions on chromosome-8, and chromosome-6 loci MICA, IRIF1, PSORS1C3, and TNFSF4 as hypermethylated in paternally transmitted disease, while PSORS1C1 was hypomethylated." (PMID 36319514, 2023). "Four of these have been previously associated with psoriasis: C6orf10, HCP5, MICA, and POUSF1." (PMID 32245788, 2020).
psoriasis (continued). "Also, rs1051792 [P(T) = 4.77E-13] in the MICA gene (rs1051792) had also been suggested to be specific for purely cutaneous manifestations of psoriasis." (PMID 31024629, 2019). "In addition, we found that SNPs from several non-HLA genes including rs2251396, rs2523454 and rs12175589 in MICA, rs7770216 in LOC729816, rs511027 in NOTCH4, rs9257483 in OR12D2 and 9262167 in IER3 were associated with psoriasis in multiple regression analyses." (PMID 22125590, 2011). "PSORS (psoriasis-susceptibility) loci harbor several genes that are involve in psoriasis; for example, HLA-Cw6, ERAP1, ERAP2, and MICA are involved in antigen presentation." (PMID 32671018, 2020). "In addition to classical HLA genes such as HLA-C, HLA-B and HLA-DQA2, we also find association of non-HLA genes in the MHC region such as POU5F1, NFKBIL1, NOTCH4, MICA, IER3 and OR12D2 with psoriasis." (PMID 22125590, 2011). "In psoriasis, it has been shown that MICA is down-regulated in lesional skin compared with non-lesional skin (p = 0.007, Gene Expression Omnibus dataset number: GDS2518)." (PMID 19680446, 2009). "The under-expression of the MICA protein might allow the unwanted cells to escape the cytolysis by NK or CD8+ T-cells, resulting in keratinocyte proliferation and the enhanced inflammation inherent to lesions of psoriasis." (PMID 19680446, 2009).
gastric cancer (13 papers, 2017 to 2025). A primary or metastatic malignant neoplasm involving the stomach. "In conclusion, MICA*009/049 allele increases the susceptibility to gastric cancer, whereas, MICA*A5 allele has a protective effect in this disease." (PMID 33868281, 2021). "Therefore, both HLA-B alleles and MICA*009/049 could to be factor risk in gastric cancer, so we suggest to consider this information for future studies." (PMID 33868281, 2021). "To evaluate the expression levels of ADAM and MICA mRNAs in gastric cancer tissues, we performed in-silico analyses of 415 gastric cancer tissues and 35 normal tissues from TCGA database." (PMID 39755747, 2025). "Based on these previous studies, we postulated that ADAMs and MICA have potential as biomarkers for screening for gastric cancer." (PMID 39755747, 2025). "In this study, we investigate the effect of DHT on the expression of MHC class I-related chain A (MICA) in SNU719 cells, a human gastric cancer cell line derived from EBV-associated gastric carcinoma." (PMID 39335190, 2024). "Thus, specific MICA/B alleles might differ in their susceptibility to H. pylori-induced shedding and this could influence the risk of developing H. pylori-induced pathologies, including gastric cancer." (PMID 38318189, 2024). "Since MICA alleles vary among human populations and generate proteins with different biological properties that may result in variable disease susceptibility, we decided to study MICA gene polymorphisms and susceptibility to gastric cancer and their relationship with the tumor progression." (PMID 33868281, 2021). "Our study demonstrates that dihydrotestosterone (DHT) enhances the immune response against EBV-associated gastric carcinoma by upregulating MICA expression and activating NK and T cells, without inducing proinflammatory cytokines." (PMID 39335190, 2024). "MICA allelic frequency in gastric cancer patients and healthy controls." (PMID 33868281, 2021). "ADAM and MICA mRNA expression in each group of stage II, III and IV gastric cancer was compared with that in stage I gastric cancer group, one by one." (PMID 39755747, 2025). "As a proof-of-concept pilot study, the expression of ADAM8, ADAM9, ADAM10, ADAM12, ADAM17, and major histocompatibility complex (MHC) class I chain-related sequence A (MICA), a ligand for NKG2D, in gastric cancer was investigated in silico using The Cancer Genome Atlas (TCGA) database." (PMID 39755747, 2025). "In gastric cancer cells, it is found that MDK induces the P38 signaling, thereby activating AP1 and increasing transcription of MHC class I chain-related proteins A and B (MICA/B)." (PMID 37240085, 2023). "It was also reported that MMP2 in renal carcinoma cells, MMP9 and MMP14 in osteosarcoma cells could increase soluble MICA and MMP9 specific inhibitor could increase MICA/B and ULBP2 in some kinds of gastric cancer cells." (PMID 34253166, 2021).
rheumatoid arthritis (13 papers, 2009 to 2025). A chronic, systemic autoimmune disorder characterized by inflammation in the synovial membranes and articular surfaces. "The MICA rs1051792 GG genotype is associated with reduced response to TNF-blockade therapy in rheumatoid arthritis patients while the heterozygous GA genotype shows better therapeutic outcomes." (PMID 40469293, 2025). "Novel gene-longevity associations included genes MICA/B (a locus previously linked to autoimmune conditions rheumatoid arthritis and multiple sclerosis), TOX, ZW10, SEMA6D, EGLN2/CYP2A6, EXOC3L2/MARK4 and C20orf187." (PMID 29227965, 2017). "Additionally, both MICA*009 and MICA*004 (MICA*A6) have been associated with Behcet disease and rheumatoid arthritis." (PMID 33868281, 2021). "For example, AIF1, MICA, ATF6B, and HSPA1L were found to be associated with an increased risk of rheumatoid arthritis (RA), while AIF1 was also associated with an increased risk of atopic dermatitis." (PMID 38835753, 2024). "The gene MICA encodes the protein major histocompatibility complex class I polypeptide-related sequence A. It is expressed in synovium of patients with rheumatoid arthritis (RA) and its implication in autoimmunity is discussed." (PMID 19409079, 2009). "In rheumatoid arthritis, MICA and MICB are aberrantly expressed in pathological tissue from affected joints and could be involved in the continuation of the autoreactive process." (PMID 24565339, 2014). "In patients with rheumatoid arthritis, large amounts of soluble MICA, presumably derived from synoviocytes, were detected in serum, and they might be stimulating autoreactive T cells." (PMID 23209462, 2012). "Levels of sMICA were significantly increased in rheumatoid arthritis (RA) patients, as compared to normal healthy controls, and RA patients with MICA-129Val/Val genotype had significantly higher sMICA levels than those with the MICA-129Met/Val or MICA-129Met/Met genotype." (PMID 34208618, 2021).